ACE (angiotensin I converting enzyme)
Diseases named in the same sentence as ACE in open-access papers (continued):
Sharing a sentence is not in itself a finding about the gene and the disease.
diabetes (continued). "RCT evidence supports the beneficial effects of ACE inhibitors and CCBs on stroke, diabetes, and kidney function." (PMID 39567981, 2024). "Angiotensin I-converting enzyme (ACE) inhibitors are recommended as first-line drugs for antihypertensive therapy, especially in patients with diabetes mellitus and cardiovascular diseases." (PMID 39408590, 2024). "We found strong protective effects of angiotensin-converting enzyme (ACE) inhibitors on diabetes whereas beta-blockers showed adverse effects." (PMID 39567981, 2024). "A recent report suggests that treating women with diabetes using an angiotensin-converting enzyme (ACE) inhibitor for six months before pregnancy onset can reduce proteinuria, improve kidney function, and contribute to favorable maternal and fetal outcomes." (PMID 38396408, 2024). "The significant effects of ACE on glycaemic disturbances suggest a correlation between ACE and diabetes mellitus, which was further confirmed by the utilization of ACE inhibitors to prevent diabetes mellitus." (PMID 39080710, 2024). "Consistent RCTs and MR evidence showed protective roles of ACE inhibitors and CCBs in stroke, kidney function, and diabetes, and showed potential harmful effects of BBs on diabetes." (PMID 39567981, 2024). "Numerous studies have demonstrated the protective and ameliorative impacts of both vitamin D analogs and ACE inhibitors against diabetes-induced oxidative stress in many tissues like the heart, kidney, and lung." (PMID 38133142, 2023). "The AFAP group had a higher proportion of patients using ACE inhibitors and a higher proportion of patients suffering from diabetes mellitus compared with the POLARx group." (PMID 37324756, 2023). "While diabetes, atrial fibrillation, valvular disease, ACE inhibitors, ischemic heart disease, COPD, sex, and initial EF were found to be important features in all sites, we observed some variations in the order and rank of these features across sites." (PMID 36609415, 2023). "The current decisive algorithm of when to start ACE-inhibition and / or diuretics in children with diabetes or obesity relies on systolic and diastolic blood pressure and on renin blood levels." (PMID 36996194, 2023). "ACE inhibitors or ARBs are the preferred first-line agent for hypertension treatment among patients with diabetes and UACR ≥300 mg/g because of their proven benefits for the prevention of CKD progression." (PMID 37238622, 2023). "The CSG Captopril in 1993 showed the benefit of an ACE inhibition on the progression of kidney disease in patients with insulin-dependent diabetes mellitus." (PMID 38105902, 2023). "Some cardiovascular and diabetes drugs commonly used in the patient in this study, such as ACE-inhibitors and SGLT-2 (discharge medicine), can also reduce uACR, which is not corrected in this study." (PMID 37563647, 2023). "A multiple linear regression analysis confirmed that ACE inhibitors decrease proteinuria independently of blood pressure, treatment duration, type of diabetes or stage of nephropathy." (PMID 37238622, 2023). "Renin-angiotensin system blockers (ACE inhibitors or ARBs) and SGLT2 inhibitors have been shown to slow the progression of CKD and reduce CV risk in individuals with diabetes and CKD, but the significant residual risk remains." (PMID 36719097, 2023). "There is evidence that metabolic complications, such as diabetes and obesity, are associated with the upregulation of RAS components such as angiotensinogen, ACE, and AT1R." (PMID 37106756, 2023). "Activation of the ACE-Ang II-AT1R pathway is one of the important pathological mechanisms of diabetes, and as such, blocking this pathway can reduce the risk of diabetes." (PMID 36748222, 2023). "ACE inhibitors are commonly used in patients with hypertension, heart failure, coronary artery disease, diabetes, and chronic renal disease." (PMID 36768666, 2023).
diabetes (continued). "About 80% of patients with diabetes were also co-prescribed with CV drugs at hospital discharge, mainly with ACE inhibitors (alone or in combination)." (PMID 36767972, 2023). "Recent evidence has shown the benefits of ACE inhibitors over ARBs in hypertensive patients and hypertensive–diabetes mellitus patients." (PMID 37299008, 2023). "Most of the identified bioactive peptides were able to inhibit key enzymes involved in the progression of cardiovascular diseases (angiotensin-converting enzyme, ACE) and diabetes (di-peptidyl-peptidase-IV, DPP-IV)." (PMID 36671770, 2023). "A previous study reported that the expressions of Ang II and ACE were increased in the spinal cord in a streptozotocin-induced diabetic neuropathic pain model." (PMID 38137500, 2023). "The FIDELIO-DKD trial included patients with type 2 diabetes mellitus with albuminuria and chronic kidney disease, and these patients were on an ACE inhibitor/ARB at baseline." (PMID 37834846, 2023). "BMI: body mass index; HF: heart failure; DM: diabetes mellitus; COPD: chronic obstructive pulmonary disease; NYHA: New York Heart Association; ACE-ARB: angiotensin-converting enzyme inhibitors - angiotensin receptor blockers." (PMID 37431349, 2023). "On the other hand, patients with diabetes that need antihypertensives should preferably continue an angiotensin-converting enzyme (ACE) inhibitor or an angiotensin II receptor blocker (ARB), due to their protective action in the kidneys." (PMID 37857987, 2023). "Under pathological conditions, ACE/Ang II can induce oxidative stress, protein glycosylation, inflammation, vasoconstriction, and increased insulin resistance in diabetes mellitus." (PMID 36253996, 2022). "Patients on beta blockers had the highest rates of prebaseline adverse cardiovascular events (AMI, heart failure, and stroke), while patients on ACE inhibitors and ARBs had higher baseline rates of diabetes." (PMID 35689299, 2022). "At this stage, treatment is initiated of all patients with diabetes with angiotensin II receptor inhibitors or blockers (ARBs) or angiotensin-converting enzyme (ACE) inhibitors to slow the rate of decline in renal function." (PMID 35562975, 2022). "The prevalence of uncontrolled hypertension and diabetes ranged from 40 to 48%, and the prevalence of ACE inhibitor use even decreased over time (45 to 36%)." (PMID 35782192, 2022). "Clinicians should be aware that nephrotoxic antibiotics such as aminoglycosides and vancomycin are more likely to induce acute kidney failure in older patients with diabetes or who take diuretics and ACE inhibitors." (PMID 35884210, 2022). "Adjustment was made for sex, age, body composition, pack years smoked, C-reactive protein, statin use, use of ACE inhibitors or ARBs, and diabetes." (PMID 35476713, 2022). "Statins, beta-blockers or ACE inhibitor treatment, body mass index, or hematocrit levels didn’t significantly influence clopidogrel response in our data set but patients with diabetes mellitus did show differential response to clopidogrel treatment." (PMID 35418564, 2022). "The study indicated that the higher ACE concentration had a significantly higher risk of CHD and diabetes in smokers after adjustment for the established risk factors." (PMID 36110446, 2022). "Persons of older age, after cataract surgery, with hyperopia, under antihypertensive drug treatment with ACE inhibitors and with diabetes have a smaller pupil." (PMID 36119137, 2022). "An increased kidney ACE2/ACE ratio in db/db is thought to represent an early compensatory effect that opposes the diabetes-mediated increase in tubular Ang II." (PMID 36361612, 2022). "With prolongation of the disease course, the effect of ACE2/Ang1-7 gradually decreased, and the effect of ACE/AngII and inflammatory factors significantly increased, which accelerated the occurrence and deterioration of diabetes." (PMID 36253996, 2022).
diabetes (continued). "Individuals of older age, after cataract surgery, under therapy with ACE inhibitors and with diabetes have a smaller pupil." (PMID 36119137, 2022). "For example, plant bioactive metabolites such as phenolics, flavonoids, and alkaloids have been shown to have ACE-inhibitory activity and thus have the potential to treat diabetes and its complications." (PMID 35502173, 2022). "The renin–angiotensin–aldosterone system‐blocker pathway prescribed ARBs/ACE inhibitors first for patients with diabetes, impaired renal function, and microalbuminuria; the standard pathway started patients on calcium channel blockers." (PMID 36153643, 2022). "In 2015, it was found that the percent of patients aged 65 and above with diabetes in Ontario who filled a prescription for an ACE inhibitor or angiotensin II receptor blocker and a statin was approximately 60 and 72%, respectively." (PMID 34895165, 2021). "The role and importance of ACE inhibitors in cardiovascular disease related to obesity and diabetes is well known." (PMID 34685777, 2021). "Model is adjusted for age, sex, cardiovascular disease, diabetes, ACE inhibitor or ARB use, BMI, SBP,DBP, Hb, K, P, Ca, Alb, TC, TG, Ccr." (PMID 34656084, 2021). "Because CKD identification in the EHR in our study was only 55%, the higher rate of ACE-inhibitor/ARB prescription compliance by providers was likely due in part to management of CVD or diabetes in these patients." (PMID 34401719, 2021). "The association of angiotensin-converting enzyme (ACE) insertion/deletion (I/D) polymorphism and the development of type 2 diabetes mellitus (T2DM) has been debated vigorously but still remains controversial." (PMID 33507688, 2021). "In our current study, we also found that the incidence of diabetes significantly triggers the increases of ACE and AT1, indicating an increase in the generation of Ang-II." (PMID 34497508, 2021). "Older patients are likely to have a higher rate of diabetes, chronic kidney failure and cardiac diseases, followed by a polypharmacy with protentional kidney toxic medications, such as diuretics and ACE inhibitors." (PMID 33468048, 2021). "The most common activities found were the dipeptidyl peptidase IV (DPP-IV) inhibitory activity related to diabetes, and the ACE and renin inhibitory activity and antithrombotic effects associated with cardiovascular diseases." (PMID 34681387, 2021). "Interventional studies have documented that angiotensin converting enzyme (ACE)-inhibitors and angiotensin receptor blockers (ARBs) reduce the incidence of type 2 diabetes mellitus (T2DM)." (PMID 33466656, 2021). "No significant statistical difference was noticed for sex, race, history of diabetes mellitus, active cancer, chronic liver disease, or home ACE inhibitor or Angiotensin II receptor blocker therapy." (PMID 34972516, 2021). "The upregulation of ACE2 has been reported as significantly high in patients with diabetes mellitus (DM) and hypertension who receive ACE inhibitors (ACEIs) or angiotensin receptor blockers (ARBs)." (PMID 34478001, 2021). "In patients with diabetes, multiple studies have reported that treatment with MR blockers, ARBs, ACE inhibitors, or a direct renin inhibitor is associated with an increase in potassium levels and a risk of severe hyperkalemia in a small number of patients." (PMID 33214722, 2021). "We test our methodology in a patient population with diabetes and heart insufficiency that becomes a therapy (beta-blockers, ACE or Aspirin)." (PMID 34112161, 2021). "Patients with idiopathic disease used more angiotensin receptor blockers (ARBs), angiotensin-converting enzyme (ACE) inhibitors, and drugs for diabetes and hyperlipidemia." (PMID 34270401, 2021). "Patients of advanced age and cardiovascular diseases or diabetes have alterations in ACE expression and Ang II signaling, likely rendering them more susceptible to further repercussions of ACE/ACE2 imbalance." (PMID 33390179, 2021).
diabetes (continued). "Diabetes induced activation of the ACE/Ang II/AT1R axis can promote cardiomyocyte and endothelial cell apoptosis, fibrosis, oxidative stress generation and inflammation, that leads to cardiac remodeling and creates a favorable condition for AF occurrence." (PMID 33602129, 2021). "The HF groups were more affected by diabetes mellitus (p = 0.042) and used more diuretics (p < 0.0001), beta-blockers (p < 0.0001), ACE-inhibitors (p < 0.0001), and statins (p = 0.004) in respect to the no HF controls." (PMID 33238655, 2020). "Years ago, smaller studies, mostly in patients with diabetes, suggested favorable anti-proteinuric effects from an ACE inhibitor/ARB combination and dual RAS blockade was also applied to other patients." (PMID 32856272, 2020). "High ACE2 levels are observed in patients with diabetes mellitus who are cured by ACE inhibitors and blockers of the angiotensin II type-I receptor (ARBs)." (PMID 33203793, 2020). "As a result of the effects of ACE and the RAS as a whole, numerous studies have shown the association between ACE function and metabolic diseases such as diabetes as well as various cancers such as pancreatic and breast cancer." (PMID 32764454, 2020). "In diabetes, to slow down the progression of diabetic nephropathy ACE inhibitors and angiotensin II receptor antagonists are first-line agents." (PMID 32874811, 2020). "In the same study, the proportion of patients with hyperkalemia for the whole study population (13.7%), patients with diabetes (19.5%) and who received ACE inhibitors and/or ARB (16.9%) where stated." (PMID 32770956, 2020). "The ATLAS trial provided information on patients with diabetes and HFrEF and the use of ACE inhibitors." (PMID 32525964, 2020). "The ACE2 level can also be increased by the nonsteroidal anti-inflammatory drug (NSAID) ibuprofen, as observed in patients with diabetes treated with ACE inhibitors." (PMID 33203793, 2020). "CCBs, ACE inhibitors, and ARBs are also expected to reduce the incidence of type 2 diabetes, but TZDs and BBs are estimated to increase the diabetes incidence." (PMID 32113622, 2020). "The authors suggested that the morbidity and mortality of COVID-19 among patients with diabetes would be higher if they used ACE inhibitors and ARBs." (PMID 32760350, 2020). "Causality between genetically determined ACE level and renal involvement in diabetes was established by ACE gene titration (1 to 3 copies) in the mouse." (PMID 31316987, 2019). "Both theoretical and experimental evidences suggest that reduced bioavailability of kinins is involved in the deleterious effect of ACE in diabetes." (PMID 31316987, 2019). "Several case studies have reported that ACE inhibitors can induce hypoglycemia in patients with diabetes." (PMID 31489273, 2019). "Studies have demonstrated that the pathogenesis of diabetes is mediated by an upregulation of ACE and a downregulation of ACE2, suggesting a compensatory mechanism." (PMID 31333451, 2019). "ACE activity has, on the opposite, deleterious end-organ effect in ischemia or diabetes, through both local angiotensin II formation and kinin depletion." (PMID 31316987, 2019). "ACE inhibitors were less commonly used in female patients (27.1% vs. 33%, p = 0.09), especially in the presence of type 2 diabetes mellitus (2.6% vs. 13.9%, p = 0.006)." (PMID 31622347, 2019). "Diabetes significantly elevated the expression of the ACE and AT1R proteins and decreased the expression of the MasR protein." (PMID 29266779, 2018). "Tolerability, a good safety profile, affordability, and a preponderance to afford cardio-renal protection in patients with diabetes make enalapril one of the most commonly prescribed angiotensin-converting enzyme (ACE) inhibitors." (PMID 29974027, 2018). "The renin angiotensin system (RAS) plays a fundamental role in the pathophysiology of diabetes and its complications, as a result angiotensin-converting enzyme (ACE) inhibitors are widely used in treating diabetic patients." (PMID 30071860, 2018).
diabetes (continued). "In people with diabetes, apart from ACE inhibitors and CCB combinations in low and moderate CVD risk individuals, other BP lowering drug combinations were not cost-effective in Tanzania." (PMID 29983644, 2018). "AKI frequently occurs in hypertensive patients taking angiotensin receptor blockers or ACE inhibitors (p=0.002), and in patients with diabetes with higher glycated haemoglobin levels (p=0.033)." (PMID 28298367, 2017). "The adjusted odds ratio for conventional risk factors (gender, age, BMI, family history of heart disease, diabetes, and obesity) further demonstrated that FVR*AG, HPA-1 b/b, and ACE* DD genotypes are independent risk factors for occurrence of CAD." (PMID 28086795, 2017). "ACE activity was significantly increased in lungs from DB mice at early and late stages of diabetes as compared to CONT mice (p = 0.045 and p = 0.026, respectively)." (PMID 28273875, 2017). "The ACE inhibitor ramipril, the ARB telmisartan, and a combination of the two drugs in patients with vascular disease or high-risk diabetes were compared in the ONTARGET study." (PMID 28725272, 2017). "Data from the Audit show that prescription of ACE inhibitors and ARBs for AI/AN patients with diabetes increased substantially, from 42% in 1997 to 74% in 2002, and then remained steady, ranging from 68% to 73% each year through 2015." (PMID 28081061, 2017). "After 21 or 40 days of diabetes onset, mouse serums and tissues were analyzed for ACE and ACE2 enzyme activities and protein expression." (PMID 28273875, 2017). "In serum samples, ACE activity was significantly increased in DB at early and late stages of diabetes as compared to CONT mice (p = 0.04 in 21-day follow up and p = 0.0003 in 40-day follow up)." (PMID 28273875, 2017). "We also observed that diabetes up-regulated ACE and ACE2 activity and protein expression in the majority of the studied tissues." (PMID 28273875, 2017). "It has been increasingly recognized that ACE inhibition demonstrates function and tissue protection of considered organs, to improve eye function of patients with diabetes mellitus and reduce the development and progression of DR." (PMID 27854313, 2016). "Distribution of DRD2/ANKK1 genotype in diabetes group, ACE and PGC1A genotypes in control group (P < 0.01, 0.005, and 0.05, respectively), and all three genetic loci in the total sample (P < 0.05) was significantly different from the expectations of HWE." (PMID 26846149, 2016). "Most evidence-based guidelines for the management of hypertension and diabetes have generally recommended the use of ACE inhibitors and ARBs in preference to other antihypertensive agents." (PMID 26954482, 2016). "Using randomized trial data and a novel evidence synthesis approach, our analyses indicate that comparisons of different RAS blockers showed similar effects of ACE inhibitors and ARBs on major cardiovascular and renal outcomes in adults with diabetes mellitus." (PMID 26954482, 2016). "It fully integrates all major cardiorenal outcomes and studies assessing ACE inhibitors, ARBs, and the DR inhibitor aliskiren in adults with diabetes, thereby providing clinicians and patients with an overall appraisal of these therapies." (PMID 26954482, 2016). "Our findings show that dual therapy with an ACE inhibitor and an ARB had no additional beneficial effect on major cardiovascular and renal outcomes when compared to an ACE inhibitor or ARB alone in adults with diabetes." (PMID 26954482, 2016). "The findings reinforce North American and European guidelines that recommend ACE inhibitors and ARBs for antihypertensive therapy in patients with diabetes." (PMID 26954482, 2016). "We believe it is unlikely that future trials will show clinically relevant advantages of ARBs over ACE inhibitors (and vice versa) in preventing cardiovascular outcomes in adults with diabetes mellitus." (PMID 26954482, 2016).